GJB4 (gap junction protein beta 4)
Description:
Structural component of gap junctions (By similarity). Gap junctions are dodecameric channels that connect the cytoplasm of adjoining cells. They are formed by the docking of two hexameric hemichannels, one from each cell membrane (By similarity). Small molecules and ions diffuse from one cell to a neighboring cell via the central pore (By similarity).
Synonyms: Cx30.3; EKV; EKVP2
Tractability: Antibody: UniProt places it where antibodies can reach, with medium confidence; UniProt predicts a signal peptide or a membrane-spanning region; its Gene Ontology location is reachable by antibodies, with medium confidence.
Gene: Protein-coding gene on chromosome 1 (34,759,740 to 34,763,724, forward strand). Ensembl gene ENSG00000189433.
Subcellular location: Cell membrane; Cell junction, gap junction
Subcellular location (Human Protein Atlas): Cell Junctions
Pathways (Reactome):
Vesicle-mediated transport: Gap junction assembly
Gene Ontology:
Molecular function: protein binding; gap junction channel activity
Biological process: cell-cell signaling; gap junction-mediated intercellular transport; cell communication; transmembrane transport
Cellular component: cell junction; connexin complex; plasma membrane; gap junction
Genetic constraint (gnomAD): Loss-of-function variants: 1 observed, 0.61 expected, observed/expected ratio (o/e) 1.65, 90% interval 0.32 to 1.92. That is too few expected variants to judge how well the gene tolerates losing a copy. Missense variants: 371 observed, 382.62 expected, observed/expected ratio (o/e) 0.97, 90% interval 0.89 to 1.06. Synonymous variants: 162 observed, 166.03 expected, observed/expected ratio (o/e) 0.98, 90% interval 0.86 to 1.11.
Homologues: Orthologues: chimpanzee GJB4 (98% identical), macaque GJB4 (96% identical), dog GJB4 (88% identical), mouse Gjb4 (86% identical), rat Gjb4 (86% identical), pig GJB4 (85% identical), guinea pig GJB4 (78% identical), rabbit GJB4 (74% identical), zebrafish gjb10 (58% identical). Paralogues in human: GJB5 (59% identical), GJB3 (58% identical), GJB1 (45% identical), GJB7 (45% identical), GJB6 (44% identical), GJB2 (43% identical), GJA4 (40% identical), GJA1 (38% identical), GJA8 (38% identical), GJA3 (37% identical), GJA10 (36% identical), GJA5 (35% identical), and 8 more.
Diseases named in the same sentence as GJB4 in open-access papers:
GJB4 is named in the same sentence as 35 diseases in open-access papers, as found by Europe PMC text mining. Sharing a sentence is not in itself a finding about the gene and the disease. The quoted sentences say what the papers report.
hearing loss (8 papers, 2011 to 2024). "Although defects in GJB4 and GJA1 in humans are known to cause hearing loss, GJB4 can be expressed in immature cardiomyocytes." (PMID 33048975, 2020). "However, the precise role of GJB4 mutations in orchestrating hearing impairment within this family context remains enigmatic." (PMID 38733163, 2024). "In both Family DE2827 and Family DE3281, heterozygosity for GJB4 p.C169W co-segregated with the hearing impairment phenotype in the pedigree, except for case I-1 of Family DE2827, which exhibited normal hearing that corresponded to his age." (PMID 23451214, 2013). "The link between GJB4 and SNHI has not yet been well-established either; however, GJB4 variants have been identified in 11 patients with non-syndromic hearing loss in Taiwan." (PMID 33396879, 2020).
erythrokeratodermia variabilis (7 papers, 2008 to 2025). A rare genetic chronic skin disorder characterized by hyperkeratosis and transient erythema. "For instance, GJB4 mutations are linked to erythrokeratodermia variabilis et progressiva (EKVP), a skin condition characterized by impaired trafficking of connexins, leading to defective gap junction assembly." (PMID 40901676, 2025). "Mutations to GJB3, GJB4, and GJA1 are linked to erythrokeratodermia variabilis et progressiva (EKVP), a disease characterized by hyperkeratotic plaques and erythematous patches." (PMID 36861039, 2023). "GJB4 and GJB3 gene mutations can result in erythrokeratodermia variabilis (EKV), and over 20 mutations in the GJB4 and GJB3 genes have been reported to be associated with EKV." (PMID 35457072, 2022). "The role of Cx30.3 in keratinocytes and epidermal health became evident when fourteen autosomal dominant mutations in the Cx30.3-encoding GJB4 gene were linked to a rare and incurable skin disorder called erythrokeratodermia variabilis et progressiva (EKVP)." (PMID 36861039, 2023). "Erythrokeratodermia variabilis (EKV) is an autosomal dominant disease characterized by erythematous lesions and hyperkeratosis caused by mutations in two epidermally expressed connexin genes, GJB3 (Cx31) and GJB4 (Cx30.3)." (PMID 19057675, 2008).
lung carcinoma (6 papers, 2019 to 2022). "A study of lung cancer cells and Cx30.3 (GJB4) revealed the increased metastatic potential and enhanced chemoresistance towards gemcitabine and etoposide in a Src-related manner." (PMID 33266154, 2020). "Recently, we found that Connexin 30.3 (Cx30.3, GJB4) promoted tumor growth, stemness and metastasis of lung cancer cells." (PMID 30642339, 2019). "At the same time, targeting GJB4 may be exploited as a modality for improving lung cancer therapy had been proved." (PMID 35372518, 2022).
deafness (4 papers, 2013 to 2024). An inherited or acquired condition characterized by the complete loss of the ability to hear from one or both ears. "In fact, digenic inheritance of nonsyndromic deafness caused by mutations in the GJB2 gene and other connexin genes, such as GJB3, GJB6, GJB4, or GJA1, have been previously reported in several deaf patients." (PMID 25388789, 2014). "In addition to the 2 families with GJB4 p.C169W, we were not able to obtain a genetic diagnosis in the other 4 ADNSHL families and the 2 ARNSHL families using the current MPS panel, although many affected members strongly suggest a genetic cause of deafness in these families." (PMID 23451214, 2013).
bladder cancer (2 papers, 2022 to 2025). "In bladder cancer, GJB4 (target protein of miR-492) promoted the proliferation and metastasis of bladder cancer cells." (PMID 40575171, 2025).
cardiomyopathy (2 papers, 2020 to 2025). A disease of the heart muscle or myocardium proper. "We evaluated the expression and the localization of GJB4 in patient’s iPSC-derived cardiomyocytes (CMs) and diseased heart from mouse, rat and human, the loss of function of GJB4 in zebrafish by CRISPR/Cas9 and the prevalence of this mutation in patients with cardiomyopathy." (PMID 33048975, 2020).
gastric cancer (2 papers, 2022 to 2025). A primary or metastatic malignant neoplasm involving the stomach. "GJB4, which has close relationship with tumors, increased the proliferation and metastasis of gastric cancer cells through Wnt/catenin beta 1 (Wnt/CTNNB1)." (PMID 40575171, 2025).
thyroid cancer (2 papers, 2022 to 2025). "GJB4 expression markedly varied in different tissues; for example, low expression was detected in normal tissues, such as liver hepatocellular carcinoma, thyroid carcinoma, and kidney renal papillary cell carcinoma, while high expression was observed in PAAD compared with other tumors." (PMID 40575171, 2025). "However, our study demonstrated that the GJB4 and ADRA1B genes may not be able to promote the thyroid cancer progression and development, and it may even be a protective gene." (PMID 35372518, 2022).
Arrhythmia (1 paper, 2020). Any cardiac rhythm other than the normal sinus rhythm. "However, further studies are required to determine how GJB4 mutations lead to the dysregulation of the GJP complex and how GJB4 affects the transition from cardiac hypertrophy and arrhythmia to heart failure." (PMID 33048975, 2020).
cardiac hypertrophy (1 paper, 2020). "Therefore, GJB4 may be an important therapeutic target for preventing the development of cardiac hypertrophy and heart failure." (PMID 33048975, 2020).
cervical cancer (1 paper, 2025). A primary or metastatic malignant neoplasm involving the cervix. "Using the same kdGJB5-sh2 lentiviral construct, we observed consistent and robust downregulation of GJB5 mRNA expression across all three cervical cancer cell types, while GJB4 mRNA levels remained unaffected." (PMID 40537499, 2025). "We also studied other GJB family proteins whose expression/roles in cervical cancer had not been previously reported, including GJB3 and GJB4." (PMID 40537499, 2025).
congenital heart defects (1 paper, 2025). "Furthermore, GJB4 plays a critical role in cardiac function, where mutations or deficiencies may disrupt electrical signaling, contributing to arrhythmias and congenital heart defects." (PMID 40901676, 2025). "Further analysis indicated that GABRP, GJB4, and RTTN were significantly associated with the occurrence of congenital heart disease." (PMID 40901676, 2025).
dysplasia (1 paper, 2009). A usually neoplastic transformation of the cell, associated with altered architectural tissue patterns. "Next to claudins, we observed up-regulation of gap junction proteins in dysplasia by 11 and 9-fold as well (Gja3, gap junction protein alpha-3 and Gjb4, gap junction protein beta-4)." (PMID 19529782, 2009).
epidermal disease (1 paper, 2024). A skin disease that involves the epidermis. "In addition to Cx26, mutations in GJB6, GJB4, GJB3 and GJA1, encoding Cx30, Cx30.3, Cx31 and Cx43, respectively have also been linked to diverse epidermal diseases." (PMID 38827992, 2024).
Netherton syndrome (1 paper, 2022). Netherton syndrome (NS) is a skin disorder characterized by congenital ichthyosiform erythroderma (CIE), a distinctive hair shaft defect (trichorrhexis invaginata; TI) and atopic manifestations. "At the beginning, Netherton syndrome and Erythrokeratoderma variabilis phenotypes were suspected, but no hair shaft abnormalities were found and no mutations in SPINK5 and EKV genes (GJB2, GJB3, GJB4, GJB6 and KDSR) were identified (data not shown)." (PMID 34983512, 2022).
tumor (6 papers, 2019 to 2025). "The expression of GJB4 was related to immune cell infiltration, tumor mutational burden expression and miRNAs." (PMID 40575171, 2025). "In patients with high expression of GJB4, 94.05% (79 of 84) exhibited tumor genetic mutations." (PMID 40575171, 2025). "GJB4 may cause ferroptosis by perturbing the tumor immune environment." (PMID 40575171, 2025). "Downregulation of GJB4 inhibited the proliferation, metastasis, and invasion of PC cells, as well as tumor growth in nude mouse subcutaneous xenografts." (PMID 40575171, 2025). "To verify that GJB4 affects tumor cells by regulating ferroptosis in PC cells, we first examined the effect of GJB4 on PC cell death." (PMID 40575171, 2025). "The data showed that GJB4 was highly expressed in PC and mainly expressed in PC tumor glandular tissues." (PMID 40575171, 2025). "Knocking down GJB4 in PC cells inhibited the tumor phenotype of these cells." (PMID 40575171, 2025). "The expression of GJB4 in patients with PC was examined using data from The Cancer Genome Atlas (TCGA), The Human Protein Atlas, Gene Expression Omnibus (GEO), Tumor Immune Estimation Resource (TIMER), microRNA Target Prediction Database (miRDB), and Encyclopedia of RNA Interactomes (ENCORI)." (PMID 40575171, 2025). "Finally, our study suggests that GJB4 inhibited ferroptosis in PC cells, thereby preserving tumor properties." (PMID 40575171, 2025). "In the future, we plan to investigate whether GJB4 changes tumor immunity by changing the tumor structure and altering the tumor environment." (PMID 40575171, 2025). "The findings of this study indicate that downregulation of GJB4 may suppress tumor characteristics by promoting ferroptosis in PC cells." (PMID 40575171, 2025). "Compared with all other cell types, GJB4 expression was observed exclusively in tumor cells." (PMID 40575171, 2025). "In the animal subcutaneous tumorigenesis experiment, we found that the tumor original cavity surrounded by tumor cells decreased in the GJB4 downregulation group, implying that GJB4 may be related to the tumor structure of PC." (PMID 40575171, 2025). "GJB4 maintains the tumor properties of PC cells by inhibiting ferroptosis." (PMID 40575171, 2025). "Better correlation was seen for GJB4 (Cx30.3) where some demethylation occurred (although the gene is still considered highly methylated), which corresponds to increased mRNA levels in both tumour subtypes." (PMID 30845770, 2019).
cancer (4 papers, 2022 to 2025). A tumor composed of atypical neoplastic, often pleomorphic cells that invade other tissues. "The relationship between GJB4 and cancer was already discussed in the section titled “Transcription, Invasion, and Malignant Transformation of Cancer”." (PMID 41154660, 2025). "GJB4 promotes cell proliferation and metastatic activities by activating the MET–AKT pathway and was suggested as a novel target for this deadly cancer." (PMID 41154660, 2025). "It was reported that GJB4 and ADRA1B genes play an essential role in developing many malignant tumours." (PMID 35372518, 2022).
skin disorder (3 papers, 2015 to 2024). Any deviation from the normal structure or function of the skin or subcutaneous tissue that is manifested by a characteristic set of symptoms and signs. "Up to now, at least 20 genes of human connexins are known, but skin disorders are only connected with mutations in GJB2 (Cx26), GJB6 (Cx30), GJB3 (Cx31), GJB4 (Cx30.3), and GJA1 (Cx43)." (PMID 25575739, 2015).
cardiac diseases (1 paper, 2020). "Further studies are necessary to reveal the complete roles of GJB4 and the prevalence and effects of GJB4 mutant in cardiac diseases in humans." (PMID 33048975, 2020). "This study investigated whether GJB4 plays an important role in human heart disease and function." (PMID 33048975, 2020).
cardiovascular disorder (1 paper, 2025). A disease involving the cardiovascular system. "Research indicates that mutations in GJB4 are closely associated with various diseases, notably cutaneous and cardiovascular disorders." (PMID 40901676, 2025).
GJB4 also shares sentences with these, for which no sentence is quoted: pancreatic cancer (3 papers); Hearing impairment (2); autosomal dominant disease (1); cataract (1); Charcot-Marie-Tooth disease (1); Clouston syndrome (1); erythrokeratoderma (1); heart failure (1); Hyperkeratosis (1); keratitis (1); KID syndrome (1); lung adenocarcinoma (1); myocardial infarction (1); psoriasis (1); velocardiofacial syndrome (1).